AR (androgen receptor)
Diseases named in the same sentence as AR in open-access papers (continued):
Sharing a sentence is not in itself a finding about the gene and the disease.
breast carcinoma (continued). "Clinical studies have shown that the androgen receptor (AR) is ubiquitously expressed in breast cancers and this could provide prognostic implication in the diagnosis and treatment of breast cancers." (PMID 28474005, 2017). "Therefore, this study investigated the network of genes that are co-expressed with AR in order to discover novel AR targets with biological significance in breast cancer." (PMID 28915724, 2017). "On the other hand, the AR has been demonstrated to be expressed in 3 main breast cancer subtypes." (PMID 28989584, 2017). "However, larger cohorts are needed for further characterization of the role of AR expression in ER− breast cancer." (PMID 28643022, 2017). "The data presented here show a strong association between AR and C1orf64 expression in breast cancer that is not limited to ER-positive tumors." (PMID 28915724, 2017). "Consequently, it is reasonable to postulate that AR expression in SDC is analogous to ERα reactivity in breast cancer, representing an apocrine phenotype." (PMID 28938615, 2017). "However, we divided breast cancer patients into AR/RB1 double-strong expression and AR/RB1 double-weak expression cohorts." (PMID 29261702, 2017). "In this review, we discussed the effect of AR in breast cancer in post-menopausal women and the opportunities that lie ahead towards developing potential therapeutic strategies which either can be used as monotherapy or in combination with the existing treatment options." (PMID 29254284, 2017). "At cellular level, co-localization of AR and ERα in breast cancer tissues implies that the nuclear interaction of AR and ERα signaling could also influence breast cancer cell growth." (PMID 28474005, 2017). "In ERα-positive breast cancer, AR was reported to predict favorable disease outcome consistently." (PMID 28474005, 2017). "It is not yet known whether similar interactions between BMP signalling and AR are found in breast cancers, and this would be a novel area of exploration and possible targeted therapy for endocrine treatment resistant breast cancers." (PMID 28733469, 2017). "Interestingly, recent investigations have identified the AR signaling pathway as a target for breast cancer treatment, with several clinical trials currently ongoing." (PMID 28487351, 2017). "None of the investigated hormones were associated with breast cancer risk when analyses were restricted to AR+ or AR+/ER+/PR+ tumors." (PMID 28720108, 2017). "This review will bring insight to a therapeutic opportunity for ER+ breast cancer patients (~80% of patients) by AR-antagonist that may reduce metastasis." (PMID 29254284, 2017). "In ER+ve breast cancers, AR-515 phosphorylation leads to an improved survival, this may be due to AR-515 increasing the rate of maturation of b-lymphocytes into plasma cells." (PMID 28415597, 2017). "Although ERα has been found to regulate the transcription of genes that promote breast cancer cell proliferation, motility, invasion, and survival, the role AR in these processes is controversial, and may depend on the hormonal milieu." (PMID 29254284, 2017). "Indeed, bicalutamide showed clinical benefit in ER/PR-negative and AR-positive breast cancers, and enzalutamide is under trial for metastatic AR-positive breast cancers." (PMID 29069872, 2017). "When associations between AR and incidence of breast cancer-related death were assessed in the ER+ and ER− subgroups separately, no prognostic impact by AR was seen in either group." (PMID 28643022, 2017). "In addition to prostate and breast cancer, there are a number of other malignancies in which AR-signaling appears to play a role in driving tumor growth." (PMID 28085048, 2017). "In addition, the distribution of AR among different breast cancer subtypes varies significantly, and the biological reasons for this variation are not well understood." (PMID 28474005, 2017).
breast carcinoma (continued). "Therefore, AR repression of C1orf64 provides another mechanism for the AR inhibitory effects on ER signaling in breast cancer cells." (PMID 28915724, 2017). "A systematic review and meta-analysis showed that positive AR expression was significantly associated with better survival of patients with early breast cancer irrespective of estrogen receptor (ER) status." (PMID 29137314, 2017). "Additionally, with the availability of more data regarding the presence of AR and the mechanism of its action regarding androgens in breast cancers, researchers now have opportunities to develop more efficacious and targeted therapies." (PMID 29254284, 2017). "AR is a commonly expressed biomarker in both normal breast and breast cancer tissues." (PMID 28915596, 2017). "AR signaling pathways show a distinct pattern, depending on the breast cancer subtypes." (PMID 28903441, 2017). "Targeting AR can be used as an alternative therapy to treat HER2 + breast cancer." (PMID 29109513, 2017). "Similarly, AR is highly expressed (80%) across all breast cancer subtypes and also negatively and positively interacts with ER signaling." (PMID 28412963, 2017). "However, current data on the role of AR in breast cancer is controversial with some groups showing a good prognosis for AR-positive TNBC patients." (PMID 28415597, 2017). "It is essential to better define AR’s prognostic role in different breast cancer subtypes." (PMID 28643022, 2017). "However, it should be noted that AR antibodies used across studies was not consistent, nor was the cutoff defining “positivity”, making it difficult to draw firm conclusion regarding the overall prevalence of AR positivity across breast cancer subtypes." (PMID 28085048, 2017). "Besides estrogen and estrogen receptor (ERα), there is emerging evidence that demonstrates the importance of androgen and androgen receptor (AR) in breast cancers." (PMID 28474005, 2017). "We subsequently evaluated the expression of androgen receptor in >2100 human breast tumor samples and 51 breast cancer cell lines and found significant heterogeneity in androgen receptor expression with enrichment at the protein and RNA level in triple-negative breast cancer." (PMID 28840192, 2017). "In contrast, the role of AR in HER2 + breast cancer is less well understood." (PMID 29109513, 2017). "Whether the AR will prove to be a clinically important target in breast cancer remains to be seen, but evidence to date does support further testing of drugs designed to inhibit this oncogenic pathway." (PMID 28085048, 2017). "Therefore, novel breast cancer therapies are targeting the AR for its observed expression in the three main breast cancer subtypes." (PMID 28551687, 2017). "Hence, we also encourage to use triple-negative breast cancer cell line (which doesn't express PR, ER, and HER2) to know effect only AR in breast cancer." (PMID 29254284, 2017). "The researchers then measured the expression of AR in more than 2100 human breast tumor samples and 51 breast cancer cell lines, and found that patients with triple-negative breast cancer, especially those who relapsed after radiation, had elevated levels of AR." (PMID 28840192, 2017). "In future, we encourage more study to determine whether by blocking AR can prevent ER-regulated metastasis Tam-R ER+ breast cancer patients through a unique molecular mechanism other than anti-estrogen therapies." (PMID 29254284, 2017). "Multiple mechanisms have been proposed to show AR and ER interactions, which indicate that AR may preferentially regulate expression of a subset of ER-responsive genes and that may be responsible for breast cancer and its progression in affected patients." (PMID 29254284, 2017). "However, follow up studies with better understanding the AR action in different subtypes of breast cancer in well-designed clinical studies using next generation of antiandrogen therapy showed encouraging results in a selected group." (PMID 28474005, 2017).
breast carcinoma (continued). "AR may be valuable for short-term prognosis, whereas additional specific markers may be needed for long-term prognosis for ER+ breast cancer, which tends to relapse late." (PMID 28643022, 2017). "In ER+ve breast cancers, high phosphorylation of AR-515 conveys a protective effect." (PMID 28415597, 2017). "AR could repress ERα activity in ERα positive breast cancer by competing with ERα for binding to regulatory regions of ERα target genes and inhibit cell proliferation." (PMID 28474005, 2017). "In the current study, this approach has been further explored by a combined analysis of two large expression datasets in breast cancer to identify an AR-gene signature of highly co-expressed genes followed by the transcriptional and functional studies of some of the key findings." (PMID 28915724, 2017). "Therefore, the study of AR co-expressed genes in large genomic datasets would provide an innovative approach to investigate AR molecular functions and novel target genes in breast cancer." (PMID 28915724, 2017). "AR is found in up to 70%–90% of all breast cancers, making it more abundant than ER or PR activity." (PMID 28245550, 2017). "Therefore, the study of C1orf64 effect on PIP expression provides a valid model to examine a possible regulatory effect for C1orf64 on AR transcriptional activity in breast cancer." (PMID 28915724, 2017). "Although previous reports indicated that androgens inhibit the progression of breast cancer, the precise mechanisms and clinical significance of AR in breast cancer remain unclear." (PMID 28067809, 2017). "AR has been shown to be expressed in 80% of BRCA2 mutated breast cancer as opposed to only 30% of BRCA1 mutated breast cancer." (PMID 28863181, 2017). "Future studies on the role of AR in breast cancer require larger cohorts, especially in the ER− subset, and the inclusion of gene expression analyses may add valuable information." (PMID 28643022, 2017). "In summary, C1orf64 is a novel AR coregulator and a 14-3-3 binding partner in breast cancer." (PMID 28915724, 2017). "As a consequence, subgroups of breast cancer patients may benefit from treatment with antiandrogens or selective AR modulators." (PMID 27923036, 2017). "The aim of this study was to validate and elaborate the previous findings of a differential role for AR on the outcome depending on ER status, using breast cancer-related death as endpoint, in an independent cohort with longer follow-up, the population-based Malmö Diet and Cancer Study (MDCS)." (PMID 28643022, 2017). "Notably, this study identifies a poorly-understood gene “C1orf64” as both a novel target gene and a coregulator of AR in breast cancer that interacts with 14-3-3 protein." (PMID 28915724, 2017). "Androgen receptor (AR, a member of the steroid hormone receptor family) status has become increasingly important as both a prognostic marker and potential therapeutic target in breast cancer." (PMID 28245550, 2017). "Therefore, the study of AR-signature genes would provide a valuable approach to better understand the molecular functions of AR in breast cancer." (PMID 28915724, 2017). "Hence it is critical to better understand biological functions of AR in breast cancer and appropriately select patients for AR targeting therapies." (PMID 28474005, 2017). "Androgen receptor (AR) is widely expressed in different subtypes of breast cancer (BC)." (PMID 29109513, 2017). "It is also important to study whether by blocking AR can prevent ER-regulated metastasis TamR ER+ breast cancer patients through a unique molecular mechanism other than anti-estrogen therapy." (PMID 29254284, 2017).
breast carcinoma (continued). "While reviewing studies, we observed that some subtypes of ER+ tumors showed that AR-agonist might be beneficial while other revealed that AR-antagonist has a positive effect on breast cancer." (PMID 29254284, 2017). "Our results suggest that AR plays a novel role in HER2 signaling and AR targeting therapy may be useful in treating HER2 + breast cancer." (PMID 29109513, 2017). "We, first, studied whether androgen administration to T47D (AR+/ER+) breast cancer cells turns into modulation of cell migration." (PMID 27746764, 2016). "This study is the first to describe AR protein expression in Thai breast cancer patients." (PMID 29083379, 2016). "Our data showed that Lin28A can induced AR expression in ER−/Her2+ breast cancer cells." (PMID 27494865, 2016). "The AR is a favorable prognostic marker and a promising therapeutic target in breast cancer." (PMID 27918430, 2016). "Having previously demonstrated the co-expression status of the Lin28A and androgen receptor (AR) in ER−/Her2+ breast cancer, we tested the hypothesis that Lin28A can activate AR and promotes growth of ER−/Her2+ breast cancer." (PMID 27494865, 2016). "In addition, we found that AR expression is correlated with increased DFS in patients with luminal breast cancer (P < 0.001), and decreased DFS in TNBC (triple negative breast cancer, P = 0.014)." (PMID 27285752, 2016). "There is growing evidence that the androgen receptor (AR) might be a new target for systemic breast cancer treatment." (PMID 29083379, 2016). "We investigated AR expression in 450 breast cancer patients." (PMID 27285752, 2016). "Our analyses demonstrate that AR is protective in ccRCC and that inhibition of androgen signaling could contribute to progression of disease, suggesting that the role of AR in breast cancer might be different from that in colon cancer and RCC." (PMID 26814892, 2016). "Based on previous findings in breast cancer, we hypothesized that also for endometrial cancer, the effect of AR signaling may be influenced by the presence of ERα." (PMID 27384477, 2016). "G protein—coupled estrogen receptor, Androgen Receptor and Hedgehog signaling pathways are emerging as novel therapeutic targets and prognostic indicators for breast cancer, based on their ability to mediate estrogenic signaling in ERα-positive or -negative breast cancer." (PMID 27548161, 2016). "ZR-75-1 is an ER-positive luminal A breast cancer cell line that expresses high levels of the AR." (PMID 27918430, 2016). "Moreover, increased AR expression has been observed in TAM-resistant breast cancer models in vitro and in vivo." (PMID 27548161, 2016). "Androgen receptor (AR) is a promising therapeutic target for breast cancer." (PMID 27374089, 2016). "AR inhibitors, in combination with other systemic agents, could be a valuable treatment for a large proportion of breast cancers." (PMID 27746764, 2016). "Specifically, androgen receptor (AR) is known to be expressed in80–90% of ER+ breast cancers and there is a recent evidence showing that in the absence of ER, AR cansubstitute for ER and initiate cell division in an ER-independent, but nuclearreceptor-dependent manner." (PMID 26884552, 2016). "In addition, a positive correlation was found between the expression of Lin28A and AR in the tumors of ER-/Her2+ breast cancer xenograft models, indicating that a positive feedback loop exists between Lin28A and AR." (PMID 27494865, 2016). "Despite or perhaps because of plentiful historical evidence, a controversy remains with respect to whether an AR agonist such as an androgen or an AR antagonist will be effective in treating breast cancer." (PMID 27918430, 2016). "AR activation by dihydrotestosterone treatment in breast cancer cells has been reported to directly suppress the E-cadherin promoter in an artificial transfection system in breast cancer cell lines and favour metastatic spread in vivo in mice." (PMID 26797644, 2016).
breast carcinoma (continued). "Although previous reports indicate that androgens inhibit the progression of breast cancer, the precise mechanisms and clinical significance of AR in breast cancer remain unclear." (PMID 26757422, 2016). "In our study, the majority of Thai breast cancer patients had tumors that expressed the AR." (PMID 29083379, 2016). "The activation of androgen receptor (AR) by DHT is beneficial for breast cancer patients." (PMID 27542970, 2016). "However, an increasing set of data support a possible role of AR as a marker of prognosis in patients with ERα-positive breast cancer." (PMID 27548161, 2016). "There is an inverse relationship between Ki-67 and AR, which suggests that AR may be a prognostic factor for breast cancer." (PMID 29083379, 2016). "Conversely, the observed decrease of androgens may be detrimental as androgens and the AR have been proposed to have protective roles in breast cancer." (PMID 27706226, 2016). "AR might also influence the site of distant metastasis in breast cancer, so more studies should be carried out to confirm this hypothesis." (PMID 27340922, 2016). "Although estrogen receptor (ER) and human epidermal growth factor receptor (HER2) are the mainstay therapeutic targets in breast cancer, the androgen receptor (AR) is evolving as a molecular target for cancers that have developed resistance to conventional treatments." (PMID 27918430, 2016). "Further studies are required to elucidate the roles of Lin28A and AR network in breast cancers." (PMID 27494865, 2016). "Enzalutamide has already shown antitumor efficacy against AR+ breast cancer in preclinical studies." (PMID 27015557, 2016). "We sought to dissect the androgen signaling pathways by exploring the associations between AR and cancer; Previous studies reported that AR could have either beneficial or deleterious effects depending on the breast cancer subtype." (PMID 27285752, 2016). "For example, AR contributes to the pathobiology of breast cancer suggesting that inhibition of androgen signaling in breast cancer could be therapeutic, and in fact clinical trials are in progress to test this concept." (PMID 26814892, 2016). "This review provides a detailed account of AR’s therapeutic role in breast cancer." (PMID 27918430, 2016). "With these goals in mind we selected a panel of prostate and breast cancer cell lines and used automated image analysis routines to quantify endogenous AR nuclear levels and localization in response to DHT, at the single cell level, using a validated N-terminal AR antibody (AR441)." (PMID 26918604, 2016). "There is emerging evidence that the androgen receptor might be an additional target for systemic breast cancer treatment; however, the role of androgens and the AR in breast cancer is still controversial." (PMID 29083379, 2016). "AR is expressed in 60-70% of breast cancer and approximate 0-53% of TNBC." (PMID 27374089, 2016). "Depending on the breast cancer molecular subtype, androgen receptor (AR) and androgen signaling may have either tumor suppressive or oncogenic role on breast cancer growth." (PMID 27340922, 2016). "The concept that NANOG may reprogram somatic cancer cells via converging on lineage master TFs such as AR/FOXA1 is likely applicable to the NANOG functions in other tumor systems such as breast cancer." (PMID 27867534, 2016). "Indeed, a phase II trial of bicalutamide, an androgen antagonist, in patients with metastatic AR+ER− breast cancer, the 6-month clinical benefit rate was 19% for bicalutamide, which established the potential of targeting AR in ER- disease." (PMID 27285752, 2016). "Preclinical models to evaluate the role of the AR in breast cancer are highly variable." (PMID 27918430, 2016).